IL33 (interleukin 33)
Diseases named in the same sentence as IL33 in open-access papers (continued):
Sharing a sentence is not in itself a finding about the gene and the disease.
eczema (7 papers, 2017 to 2025). "IL-33, a cytokine produced by epithelial cells, can polarize Th2 responses and exacerbate eczema when upregulated." (PMID 39851511, 2025). "IL-33 transgenic mice expressing IL-33 in keratinocytes spontaneously develop AD-like eczema, suggesting that IL-33 alone can drive AD pathogenesis." (PMID 40230853, 2025). "IL-33 transgenic mice, which express IL-33 specifically in keratinocytes, spontaneously develop AD-like eczema, suggesting that IL-33 is sufficient for the development of AD." (PMID 38203432, 2023). "(c) The immunological system of eczema focused on T helper type 2 (Th2) cell-derived cytokines, including interleukin (IL)-4 and IL-13, and keratinocyte-derived cytokines, as well as thymic stromal lymphopoietin (TSLP) and IL-33, which contribute to Th2-mediated skin inflammation in AD." (PMID 41011120, 2025).
encephalitis (7 papers, 2016 to 2021). An acute inflammatory process affecting the brain parenchyma. "To better understand the pathogenic mechanism of IL-33 signaling on ROCV-induced encephalitis, we explored the cellular composition of CNS tissue and the cytokines being produced on WT versus ST2−/− mice." (PMID 27334012, 2016). "In addition, IL-33 can attenuate brain parenchymal damage caused by encephalitis by regulating iNOS." (PMID 33854693, 2021). "IL-33 signaling pathway is also shown to be essential in attenuating viral-induced encephalitis development by downregulating iNOS expression in the CNS." (PMID 30515150, 2018). "Here, in this study, we demonstrate that IL-33 has a protective role on experimental viral encephalitis." (PMID 27334012, 2016). "IL-33 is essential to attenuate viral-encephalitis by downregulating iNOS expression in the CNS." (PMID 29408905, 2018). "In conclusion, our data suggest that IL-33 might play a crucial role in the pathogenesis of virus-induced encephalitis by controlling the local Th1/Th2 balance." (PMID 27334012, 2016). "In addition, IL-33 was also reported to be essential to attenuate viral-induced encephalitis." (PMID 28320438, 2017). "Finally, the data presented here may contribute to the design of new therapies to viral encephalitis based on the benefits of IL-33 administration or the blockade of its receptor ST2 to avoid extensive damage elicited by the immune response to CNS insults." (PMID 27334012, 2016). "IL-33 signaling through T1/ST2 was shown to be required for controlling Toxoplasma infection in the brain and preventing the development of encephalitis." (PMID 32363166, 2020). "However, the role of IL-33 on viral encephalitis remains unclear." (PMID 27334012, 2016). "IL-33 signaling was also required for controlling toxoplasma infection in the brain and preventing the development of encephalitis, while absence of IL-33 receptor/ST2 attenuated neutrophilic inflammation and ileitis in an oral model of toxoplasmosis." (PMID 32363166, 2020).
liver cirrhosis (7 papers, 2015 to 2024). "Significantly higher serum levels of IL-33 have been observed in patients with liver cirrhosis compared to control." (PMID 36110858, 2022). "Consistent with data from mice, serum levels of IL-33 are elevated in patients with liver cirrhosis." (PMID 26549942, 2015). "The roles of IL-33 in liver cirrhosis will be described in a subsequent section." (PMID 26549942, 2015). "In addition, It has been found that patients with liver cirrhosis have an increased level of IL-33." (PMID 39350187, 2024). "Therefore, we propose that IL-33 may be considered a necroptotic DAMP that contributes to liver cirrhosis-related fibrosis." (PMID 36110858, 2022). "The mechanism of IL-33 release during liver cirrhosis has not been elucidated; however, necroptosis has recently been shown to directly induce the release of nuclear IL-33 in its full-length form." (PMID 36110858, 2022).
lung adenocarcinoma (7 papers, 2016 to 2025). A carcinoma that arises from the lung and is characterized by the presence of malignant glandular epithelial cells. "On the other hand, PEBP1, FLT3 and IL33 were adversely associated with the outcomes of lung adenocarcinoma patients." (PMID 39311766, 2024). "The survival curve analysis performed using the SurvExpress database showed that the high risk population with lower expression of IL33 has poorer survival outcomes for lung adenocarcinoma patients." (PMID 29285217, 2017). "Taken together, these data suggest that IL-33 is primarily expressed in fibroblasts within lung adenocarcinoma tissues." (PMID 40216748, 2025). "We used the Kaplan-Meier Plotter website to explore the clinical relevance of IL-33 expression in lung adenocarcinoma (LUAD)." (PMID 40216748, 2025). "IL-33 can induce CYLD-activated DCs in mouse lung adenocarcinomas, thereby inducing the proliferation of T cells and the secretion of IL-17 to eradicate the tumors." (PMID 35634336, 2022). "In lung adenocarcinoma model, IL-33 can activate NK in a TNF-α-dependent manner through activating the NF-κB signaling pathway, and promoting the proliferation and activation of CD8+ T cells, consequently inhibiting tumor metastasis." (PMID 35634336, 2022). "We examined the relationship between IL-33 expression in tumor tissues and the overall survival time in patients suffering from adenocarcinoma of the lung." (PMID 29499051, 2018). "We believe this is true down-regulation of IL-33 during tumor progression because, based on mouse studies, alveolar type II cells are believed to be the cell origin of lung adenocarcinoma." (PMID 29499051, 2018). "The mRNA expression of IL33 is significantly downregulated in lung adenocarcinoma compared to normal tissue." (PMID 29285217, 2017). "We also found that IL33 expression is decreased in lung adenocarcinoma identified from the GSE10072 array." (PMID 29285217, 2017). "Since IL-33 was highly expressed in normal alveolar type II cells in both human and mice and expression was much reduced in lung adenocarcinoma cells, we believe it is appropriate to conclude that IL-33 is down-regulated in adenocarcinoma of lung compared to normal tissue cells." (PMID 29499051, 2018). "The prognostic values of IL33 in lung adenocarcinoma was illustrated as a forest plot." (PMID 29285217, 2017). "In our analysis, we found that IL33 may have tumor suppressor functions in lung adenocarcinoma." (PMID 29285217, 2017). "To investigate the distribution of IL-33 in the TME, we utilized the Visium spatial transcriptomics technology from 10X Genomics on biopsy tissue sections from a patient with lung adenocarcinoma." (PMID 40216748, 2025). "The analysis of the effects from each gene expression on survival outcome indicated that 6 genes (AGR2, SPDEF, CDKN2A, CLDN3, SFN, and PHLDA2) play oncogenic roles, and 7 genes (PDK4, FMO2, CPED1, GNG11, IL33, BTNL9, and FABP4) act as tumor suppressors in lung adenocarcinoma." (PMID 29285217, 2017). "However, since the genetic interactions of hsa-miR-183-5p-BTNL9, hsa-miR-33b-5p-CPED1, hsa-miR-429-CPED1, hsa-miR-182-5p-FMO2, hsa-miR-130b-5p-IL33, and hsa-miR-542-3p-IL33 have not been identified, these altered genetic regulations may play important roles in the progression of lung adenocarcinoma." (PMID 29285217, 2017).
osteosarcoma (7 papers, 2017 to 2025). A usually aggressive malignant bone-forming mesenchymal neoplasm, predominantly affecting adolescents and young adults. "In osteosarcoma patients, low levels of IL-33 were associated with protection when compared with controls." (PMID 40352809, 2025). "We noticed that IL33 was exclusively expressed in ACKR1_EC sub‐clusters, and osteosarcoma patients with higher IL33 mRNA levels were associated with better OS and EFS." (PMID 36305631, 2022). "On top of that, Kang and colleagues genotyped common variants in the IL33 gene and found that the A-allele of rs1048274 was associated to survival in a osteosarcoma patient cohort of Chinese ancestry." (PMID 36536332, 2022). "Furthermore, expression quantitative trait locus (eQTL) analysis showed that the T-allele of rs55933544 was significantly associated with a decreased IL33 expression and lower IL33 expression was independently associated with worse osteosarcoma patient survival." (PMID 36536332, 2022). "In osteosarcoma, IL33 plays a role in osteosarcoma cell viability in in vitro experiments mediated through the PI3K/AKT pathway." (PMID 36536332, 2022). "The aim of this study was to investigate the association of two functional polymorphisms (IL‐33 rs7025417 and ST2 rs3821204) with osteosarcoma (OS) risk." (PMID 29797504, 2018). "In the TARGET‐osteosarcoma dataset, the GLDC mRNA level was negatively associated with the prognosis of patients with osteosarcoma, indicating that rs55933544 may influence prognosis by regulating IL33 and/or GLDC." (PMID 36305631, 2022).
steatosis (7 papers, 2016 to 2024). Increased lipid within the cytoplasm of cells. "The beneficial effect of exogenous IL-33 on steatosis was attributed to a shift from an inflammatory Th1 response to an anti-inflammatory Th2 response." (PMID 30213101, 2018). "Our results demonstrate steatosis-induced hepatocellular damage marked by ALT/IL-1αrelease and shifts in the form of decreased activation of NF-κB and IL-33 aimed at reducing injury." (PMID 31034519, 2019). "IL-33 deficiency did not affect the severity of steatohepatitis at the histological level: the degree of steatosis, and the frequency of lobular infiltrates and ballooning hepatocytes was similar between WT-HFD and IL-33 KO-HFD mice." (PMID 28611297, 2017). "Hematoxylin and eosin staining revealed hepatic steatosis and ballooning degeneration of hepatocytes in the liver tissues of HFD-fed mice, which was attenuated by treatment with IL-33." (PMID 27172901, 2016). "Histological results indicated marked macrovesicular steatosis and ballooning degeneration in hepatocytes of MCD-fed mice, which was attenuated by treatment with IL-33." (PMID 27172901, 2016). "While lack of IL-33 did not alter pathology, ST2 deficiency aggravated alcohol-induced steatosis and liver damage associated with NFκB activation and inflammatory cytokine expression in hepatic macrophages." (PMID 30213101, 2018). "Undetectable levels of serum IL-33 and stable liver HMGB1 suggests the level of hepatocyte damage in our simple steatosis model is not severe enough to result in systemic release of these alarmins into the serum." (PMID 31034519, 2019).
tuberculosis (7 papers, 2014 to 2025). A chronic, recurrent infection caused by the bacterium Mycobacterium tuberculosis. "Pleural IL-33 is a novel, fast (4.5 h), reliable biomarker assay for the differentiation of pleural effusion especially tuberculosis from the malignant pleural effusion." (PMID 31238901, 2019). "The increased level of plasma IL-33 reveals that IL-33 measurement in HIV-1 monoinfected patients may represent an early predictor of development of tuberculosis." (PMID 38035159, 2023). "Our work indicates that IL-33 might be an alternative therapeutic treatment for severe tuberculosis." (PMID 28128217, 2017). "IFN-γ directly regulates the innate immunity against tuberculosis, therefore IL-33 may modulate and enhance host immunity through the induction of IFN-γ in tuberculous pleurisy." (PMID 24959294, 2014). "Tuberculosis triggers a type 1 immune response characterized by IL-12, IFN-γ, and TNF-α production, while toxocariasis elicits a type 2 response, mediated by cytokines such as IL-4, IL-5, IL-13, and IL-33." (PMID 40943043, 2025). "The combined value of the three tests for the diagnosis of tuberculous pleurisy was investigated to identify the correlation between pleural fluid interleukin-33 (IL-33), adenosine deaminase (ADA)and peripheral blood tuberculosis T cell spot detection (T-SPOT.TB)." (PMID 34425761, 2021). "This study aimed to evaluate the level of IL-33 in plasma of HIV and M. tuberculosis (HIV/TB) coinfected patients compared to patients with respective mono infections in Yaoundé." (PMID 38035159, 2023). "However, IL-33 was described as a promising adjuvant that increased the immunogenicity of a DNA vaccine expressing M. tuberculosis antigen 85B55, suggesting that it could be an effective tool for the development of vaccines against TB." (PMID 28128217, 2017). "Our data indicate a new mechanism for enhanced resistance to M. tuberculosis infection mediated by IL-33/ST2 axis and suggests an alternative therapeutic treatment for severe TB." (PMID 28128217, 2017). "Due that plasma levels of IL-6, IFN-γ, IL-33, and CHIT1 appear to differentiate severe TB from mild APTB during the first 2 months of anti-tuberculosis treatment, we conducted an analysis using ROC curves to determine the diagnostic accuracy of these molecules, concerning APTB severity." (PMID 38137331, 2023).
ulcer (7 papers, 2013 to 2025). "In contrast, ulcer-related myofibroblasts help regulate the inflammatory microenvironment by secreting IL-33 and play a role in mucosal repair or fibrosis." (PMID 40584713, 2025). "Gene analysis results confirmed that expression changes occurred in genes of key regulators of wound healing, such as chemokines, MMP-1, 9, CSF-2, and IL-33, and that such genetic changes enhanced wound healing in ulcers." (PMID 37508509, 2023). "In particular, IL-33 was inversely correlated to the number of ulcers (r Spearman −0.638, p = 0.048) while T-bet, Gata-3 and IFN-γ were directly correlated with the number of ulcers (r Spearman 0.792, p = 0.011)." (PMID 24520333, 2014). "Perhaps locally applying IL-5 or IL-33 to an ulcer bed could attract eosinophils to promote fibrosis and closure (risky in terms of inflammation, but conceptually interesting)." (PMID 40860650, 2025). "The main source of IL-33 in UC lesions was ulcer-associated myofibroblasts, and interestingly, this is a significant difference compared to patients with CD, where IL-33-positive myofibroblasts were almost absent near deep intestinal ulcers." (PMID 40565217, 2025).
Airway obstruction (6 papers, 2020 to 2024). Obstruction of conducting airways of the lung. "Future experiments will be warranted to determine the effect of Tollip deficiency-mediated IL-33 release on airway obstruction." (PMID 38124753, 2023). "We believe our study may help to understand the role of TSLP, IL-33, and IL-17A in a positive feedback loop between the airway epithelium and inflammatory cells infiltrating the airways in obstructive lung diseases." (PMID 32842623, 2020).
allergic contact dermatitis (6 papers, 2018 to 2025). An inflammatory skin condition caused by an immune response to direct contact between the skin and an allergen. "The expression of miR-155 in IL-33-treated peritoneal MC isolated from allergic contact dermatitis rats was increased in comparison to IL-33-treated naive MC, resulting in the increased production of inflammatory cytokines such as IL-6 and TNF-α." (PMID 31052286, 2019). "Moreover, in a murine model of allergic contact dermatitis, blocking IL-33/ST2 signaling, either IL-33 or ST2 with an appropriate antibody, alleviated both inflammation and pruritus." (PMID 41155460, 2025). "In addition, our recent work found that IL-33 released by keratinocytes can activate peripheral sensory neurons via promoting Ca2+ influx through TRPA1/TRPV1 channels in ST2 dependent mechanism, resulting in potentiation of skin inflammation and pruritus in a mouse allergic contact dermatitis model." (PMID 33204337, 2020).
bipolar disorder (6 papers, 2016 to 2024). A disorder of the brain that causes unusual shifts in mood, energy, activity levels and the ability to carry out day-to-day tasks. "On the contrary, another study found that IL-33 levels in the blood were higher in bipolar disorder patients than healthy controls." (PMID 35224555, 2022). "Increased inflammatory biomarkers such as tumor necrosis factor-alpha (TNF)-α, IL-6, cyclooxygenase (COX)-2, and arachidonic acid (AA) were identified in bipolar disorder patients compared to healthy controls without mental illnesses; however, IL-10 and IL-33 levels remained unchanged." (PMID 35224555, 2022).
bronchopulmonary dysplasia (6 papers, 2020 to 2024). Bronchopulmonary dysplasia is a chronic respiratory disease that results from complications related to lung injury during the treatment of infant acute respiratory distress syndrome in low-birth-weight premature infants or from abnormal lung development in older infants. "In alveolar epithelial cells from mice with bronchopulmonary dysplasia, inhibition of YTHDC1 led to a decrease in IL-33 mRNA and protein expression, which in turn inhibited alveolar epithelial cell apoptosis and alleviated lung injury induced by hyperoxia treatment for bronchopulmonary dysplasia." (PMID 39108751, 2024).
cervical carcinoma (6 papers, 2013 to 2025). A carcinoma arising from either the exocervical squamous epithelium or the endocervical glandular epithelium. "In contrast, a recent study has demonstrated that the IL-33-mediated IL-33-ILC2s-IL-13-M-MDSCs axis plays a primary tumor-promoting role in cervical cancer." (PMID 40539072, 2025). "In breast and cervical cancer, increased expression of IL-33 has been observed in tumor cells from patients with LN metastases, suggesting that IL-33/ST2 might participate in invasion and metastasis by remodeling primary and metastatic tumor microenvironment." (PMID 31281317, 2019). "While in cervical cancer, IL-33 related necroptosis could work as a possible pioneer for immunotherapy in cervical cancer." (PMID 30619376, 2018). "Moreover, while still transcribed in immortalized keratinocytes, the same transcriptional down-regulation was also detected in cervical carcinoma cells when other cytokines such as IL-1α, IL-18 and IL-33 were monitored by q-PCR." (PMID 23935506, 2013).
childhood asthma (6 papers, 2020 to 2023). "Investigating the efficacy of a combination of dupilumab and SAR440340, an antibody directed against IL-33, may shed light on the role of IL-33 in severe childhood asthma." (PMID 32188435, 2020).